GSK3B (glycogen synthase kinase 3 beta)
Diseases named in the same sentence as GSK3B in open-access papers (continued):
Sharing a sentence is not in itself a finding about the gene and the disease.
renal fibrosis (continued). "Our data indicated that this increased GSK3β activity may confer a permissive effect on TEC fibrogenic plasticity and contribute to renal fibrosis." (PMID 33931588, 2021). "Studies have found that by down-regulating the AKT/GSK-3β signaling pathway, AS-IV can reduce the expression of α-SMA, type I collagen and fibronectin induced by TGF-β1 and inhibits the epithelial-to-mesenchymal transition of rat renal tubular epithelial cells and delays renal fibrosis." (PMID 39705287, 2024). "Therefore, the change in ER stress regulated the expression of GSK-3β/Snail, while the change in GSK-3β did not affect the state of ER stress during the anti-renal fibrosis action of Renalase." (PMID 37082730, 2023). "Moreover, targeting of GSK3β in renal tubules via genetic knockout or by lithium, a standard inhibitor of GSK3β and FDA-approved mood stabilizer, effectively preserved renal TEC phenotypes and ameliorated renal fibrosis in mice with FA nephropathy." (PMID 33931588, 2021). "Similarly, inhibiting AKT activation and GSK-3β phosphorylation may attenuate EMT-related E-cadherin inhibition, α-SMA elevation, and morphological transformation into a myofibroblast-like phenotype, thereby ameliorating proteinuria-induced tubular EMT and ultimately reducing renal fibrosis." (PMID 33052244, 2020).
osteoporosis (36 papers, 2007 to 2026). A condition of reduced bone mass, with decreased cortical thickness and a decrease in the number and size of the trabeculae of cancellous bone (but normal chemical composition), resulting in increased fracture incidence. "Activation of GSK3β was associated with osteoporosis in animals induced by high-fat diet, glucocorticoid, and STZ." (PMID 38672518, 2024). "The expression of GSK3β (activation of GSK3β) was also increased in STZ-induced diabetic rats with osteoporosis, which was associated with the increased inflammatory response and impaired glycaemic control in this model." (PMID 38672518, 2024). "According to a model of senile osteoporosis, dietary phlorizin increases β-catenin activity by inhibiting GSK-3β and promotes osteoblastogenic bone formation." (PMID 41415572, 2025). "Transcriptomic and metabolomic data collectively reveal that the P2X7 receptor can impact the pathogenesis of osteoporosis through the PI3K-Akt-GSK3β signaling pathway." (PMID 38977961, 2024). "P2X7 functions through mediating multiple signaling pathways in bone diseases, with the PI3K-Akt-GSK3β signaling pathway being a crucial pathway in osteoporosis-related research." (PMID 38977961, 2024). "To deepen our understanding of the role of the PI3K-Akt-GSK3β signaling pathway in the pathogenesis of osteoporosis, we used WT mice and P2X7f/f; LysM-cre mice as experimental subjects." (PMID 38977961, 2024). "Luteolin is a flavonoid found in many herbal extracts with antioxidant, anti-inflammatory and anti-tumor activities, and has been shown to reduce glucocorticoid-induced osteoporosis by modulating the ERK/Lrp-5/GSK-3β signaling pathway in vitro and in vivo." (PMID 36210811, 2022). "Our previous study showed that the dihydrochalcone phlorizin stimulated osteoblastogenic bone formation through enhancing β-catenin activity via glycogen synthase kinase-3β (GSK-3β) inhibition in a model of senile osteoporosis." (PMID 34830274, 2021). "In animal models of steroid-induced osteoporosis, lithium can activate the Wnt signaling pathway by inhibiting GSK-3β activity, and reverse osteoporosis by improving osteoblast activity and inhibiting osteoclast mediated bone resorption." (PMID 33649409, 2021). "On the other hand, further in vivo studies should be arranged to verify the preventive effect of Cur on osteoporosis and corroborate the role of GSK3β-Nrf2 singling pathway." (PMID 32612986, 2020). "Using ovariectomized rats as a model, this work demonstrated that the AKT/GSK3β/β-catenin/NFATC1 signaling pathway is a target in osteoporosis treatment." (PMID 31196133, 2019). "GSK3B (glycogen synthase kinase 3 beta) is a serine-threonine kinase involved in energy metabolism, neuronal cell development, inflammation, and osteoporosis that also plays an important role in transcriptional regulation and oncogenic signaling." (PMID 28427240, 2017). "However, only one study reported that GSK3β gene expression (activity) was lowered in glucocorticoid-induced osteoporosis, which was then increased following improvement of bone parameters after treatment with ferulic acid." (PMID 38672518, 2024). "Interestingly, our previous study has shown that DEC1 stimulates the PI3KCA/Akt/GSK3β signaling and prevents osteopenia/osteoporosis." (PMID 36739947, 2023). "Likewise, AZD2858, a Gsk3 inhibitor, significantly increases the bone mass in rats by upregulating the β-catenin levels, further validating this inhibitor in the osteoporosis therapy by targeting the ROCK/JAK/GSK3β signaling." (PMID 33655459, 2021). "In addition, phlorizin promoted β-catenin-dependent osteoblastogenic bone formation via GSK-3β inhibition in a model of senile osteoporosis." (PMID 34830274, 2021). "Our findings demonstrated that Cur could protect osteoblasts against OS-induced dysfunction via GSK3β-Nrf2 signaling and provide a promising way for osteoporosis treatment." (PMID 32612986, 2020).
osteoporosis (continued). "The administration of curcumin significantly decreases H2O2 that is induced by oxidative damages and cell toxicity in osteoblast-like cells via retaining the glycogen synthase kinase 3 beta (GSK3β)-Nrf2 signaling pathway, which provides a possible promising osteoporosis treatment strategy." (PMID 33291560, 2020). "Liu44 further demonstrated in a mouse orthopedic study that a singleton therapeutic agent for osteoporosis can gain a coupled effect on the stimulation of bone formation by the Wnt/GSK3β/β-catenin pathway and on the suppression of bone resorption by the NF-κB/c-fos/NFATc1 pathway." (PMID 28931847, 2017). "Taken together, these observations strongly suggest that the GSK-3β suppression may yield novel therapeutics to treat bone catabolic disorders like cleidocranial dysplasia and osteoporosis." (PMID 17786208, 2007). "GSK-3β is a crucial negative regulator of canonical Wnt/β-catenin signaling, suggesting GSK-3β as a potential molecular target for the treatment of osteoporosis." (PMID 41415572, 2025). "Recent studies have suggested that fisetin can improve the level of bone mineral density in ovariectomy-induced osteoporosis model rats and promote osteogenesis in MC3T3-E1 cells and vertebrae formation in zebrafish larvae via the GSK-3β/β-catenin pathways." (PMID 37087476, 2023). "Yigutang can not only prevent and treat osteoporosis through the classic Wnt/β-catenin signaling pathway but also achieve the purpose of preventing and curing osteoporosis through the P13K/AKT/GSK-3β signaling pathway." (PMID 34239593, 2021). "Gossypol also significantly enhanced medullary and cortical BMD, the expression of Wnt protein, β-catenin, and GSK-3β, as well as the mRNA levels of osteogenesis-related genes, including osteocalcin, Runx2, OPG, and COL1A1, in mice with osteoporosis compared to control mice." (PMID 39606935, 2025). "The biological functions of TERT, β-catenin, and GSK3β in osteoporosis and the effects of LiCl on their expression have not been explored." (PMID 37862118, 2023). "In the present study, we found that Periostin was reduced in BMSCs derived from the osteoporosis rat model and that overexpression of periostin could enhance the osteogenic ability of BMSCs, in part by activating the ILK/Akt/GSK3β axis." (PMID 34591063, 2021). "However, the precise mechanisms of action of the P2X7 receptor and the PI3K-Akt-GSK3β signaling pathway in osteoporosis are not yet fully understood." (PMID 38977961, 2024). "In summary, our experiments confirmed that the GSK3β/β-catenin/TERT pathway could regulate the osteogenic differentiation and apoptosis of BMSCs and that TERT might be a promising target for the future treatment of osteoporosis." (PMID 37862118, 2023). "Therefore, this study applied a low-dose combination of LiCl and LY294002 to treat osteoporosis and to test whether this method can inhibit osteoclast activity and promote osteoblast activity through inhibition of the AKT/GSK3β/β-catenin/NFATC1 pathway." (PMID 31196133, 2019). "Understanding of the molecular mechanisms involved in promoting bone density has been important to the development of multiple drug therapies for osteoporosis, such as the capthepsin K inhibitors Odanacatib and Balicatib, anti-SOST antibodies, anti-Dkk1 antibodies, and GSK3β and Sfrp1 inhibitors." (PMID 27483347, 2016). "No result on GSK3β expression was reported in the titanium-induced osteolysis, or LPS- and RANKL-induced osteoporosis." (PMID 38672518, 2024). "Regarding the patients with advanced osteoporosis (Group 4), we found out negative correlations between LS T-score and the REL of: GSK3B (R=−0.810, p = 0.008)." (PMID 33357212, 2021).
ischemic stroke (35 papers, 2013 to 2026). A stroke disorder caused by obstruction of blood flow to the brain, due to thrombotic (local blood clot formation) or embolic (due to a blood clot or other material traveling from another site) event. "Our results show that the active compounds from DB closely relate to PI3K, Bcl-2, COX-2, p38, CREB, GSK3β, and TrkB, most of which were associated with oxidative stress and brain inflammation cause of ischemic stroke." (PMID 32508949, 2020). "Additionally, the dysregulation of GSK3β has been linked with the cognitive abnormalities and pathologies of AD, schizophrenia, fragile-X mental retardation, mood disorders, ischemic stroke and other excitotoxicity-related disorders." (PMID 33809219, 2021). "However, to our knowledge, the underlying mechanism of GSK‐3β that governs the anti‐inflammatory microglia/macrophages polarization processes caused by SPC after ischemic stroke is still unknown." (PMID 34370899, 2021). "However, whether GSK3β inhibitor can block the ischemic stroke-induced formation of glial scar associated with suppressing astrocyte-mediated inflammation and its underlying mechanisms are largely unclear." (PMID 32595496, 2020). "The AKT/GSK3β/Cyclin D1 pathway was predicted to be a potential mechanism of FDT in intervening ischemic stroke." (PMID 41767015, 2026). "Our findings reveal that NBP treatment enhances angiogenesis following ischemic stroke by upregulating VEGF via the Akt/GSK‐3β signaling pathway." (PMID 41373119, 2025). "In conclusion, NBP enhances recovery after ischemic stroke by promoting cortical angiogenesis and vasodilation through activation of the Akt/GSK‐3β pathway." (PMID 41373119, 2025). "Glycogen synthase kinase 3β (GSK3β) is a highly conserved serine/threonine kinase involved in various diseases, including ischemic stroke, neurodegenerative disorders, and cancer." (PMID 41022323, 2025). "GSK3β is considered a critical therapeutic target for ischemic stroke, as inhibiting it can protect the nervous system from oxidative stress or inflammation-mediated damage." (PMID 41022323, 2025). "GSK3β has emerged as a potential therapeutic target in ischemic stroke through its regulation of oxidative stress and inflammatory processes." (PMID 41022323, 2025). "The GSK3β inhibitor e2-I showed similar immunomodulatory effects on BV2 cells under OGD/R conditions, similarly revealing the protective role of GSK3β S/T-P kinase activity in ischemic stroke." (PMID 41022323, 2025). "Protected experimental ischemic stroke by enhancing anti-inflammatory M2 microglia polarization through GSK-3β/Nrf2 pathway." (PMID 37962460, 2024). "Many potential anti-stroke candidates, such as OCT4B-190 and Apelin 13, produced neuroprotective effects against ischemic stroke via inhibiting GSK-3β." (PMID 36015166, 2022). "This study confirmed the relationship of miR-429 and ischemic stroke, found the downstream target of miR-429, and revealed the regulation of miR-429 on the activity of GSK-3β/β-catenin pathway." (PMID 34966442, 2021). "Neuroinflammation, a key aspect of AD eitiology and of central importance to injury sustained after ischemic stroke and subarachnoid hemorrhage, is reduced by phosphorylation of GSK3β." (PMID 33809219, 2021). "Accumulating evidence has revealed that the GSK-3β/HO-1 pathway modulates oxidative stress levels in the progression and treatment of ischemic stroke." (PMID 35056059, 2021). "It has been reported that glycine improved ischemic stroke via activation of the GSK-3β/HO-1 pathway." (PMID 33935731, 2021). "The safety and feasibility of using GSK-3β regulators, such as OA, for treating ischemic stroke should be carefully monitored in the future." (PMID 35056059, 2021). "As such, the involvement of other mechanisms, in addition to the GSK-3β/HO-1 pathway-mediated effects, during OA-mediated treatment of ischemic stroke is unclear and warrants further investigation." (PMID 35056059, 2021).
ischemic stroke (continued). "As a result, enhancement of HO-1 via GSK-3β inactivation (GSK-3β/HO-1 pathway) plays a crucial role in improving ischemic stroke." (PMID 33935731, 2021). "In conclusion, the present report is the first which demonstrates that pre-treatment of a rat model of ischemic stroke with AGNHW for 7 consecutive days effectively curtailed the injury done in the ischemic brain via activation of GSK-3β-mediated HO-1 pathway." (PMID 33935731, 2021). "Accumulating evidence has demonstrated that suppression of GSK-3β activity results in overexpression of the HO-1 protein, subsequently ameliorating ischemic stroke-mediated neuronal injury." (PMID 35056059, 2021). "Recent studies targeted Akt/GSK-3β-mediated Nrf2 activation as a therapeutic potential in CNS diseases, such as AD and ischemic stroke." (PMID 34706756, 2021). "The protective effect of inhibition of glycogen synthase kinase-3β (GSK3β) or receptor-interacting protein 1 kinase (RIP1K) on ischemic stroke has been previously reported." (PMID 32595496, 2020). "In conclusion, inhibition of GSK3β or RIP1K reduced glial scar formation induced by ischemic stroke." (PMID 32595496, 2020). "The current study examined the effects of RIP1K and GSK3β on ischemic stroke-induced glial scar formation." (PMID 32595496, 2020). "Both inhibition of RIP1K by Nec-1 and inhibition of GSK3β by SB216763 produce a protective effect against ischemic stroke." (PMID 32595496, 2020). "GK exerted a similar effect as Mdivi-1, i.e. increased GSK-3β phosphorylation and attenuated CypD-dependent mPTP opening, thus confirming that GK attenuated brain injury after ischemic stroke by maintaining mitochondrial structural and functional integrity." (PMID 28591721, 2017). "Although glycogen synthase kinase 3β (GSK3β) is a key regulator in ischemic stroke, the contribution of its proline-directed kinase activity to cellular dysfunction and disease progression remains unclear." (PMID 42261803, 2026). "The blockade of GSK3β has been shown to produce neuroprotective effects against ischemic stroke." (PMID 36015166, 2022). "The ERK and GSK3β signaling pathways were involved in ischemic stroke." (PMID 36015166, 2022). "Because, we also observed that CK2 inhibition improved axon function recovery by decreasing the inactivation of GSK3β in WM, these findings suggest that GSK3β could be a common target to protect both GM and WM after ischemic stroke." (PMID 35911974, 2022). "Beyond ischemic stroke, natural antioxidative compounds that regulate the GSK-3β/HO-1 signaling pathway may hold significant potential in the treatment of aging-related neurodegenerative diseases." (PMID 35056059, 2021). "Counteraction of oxidation via inhibition of GSK-3β may, therefore, be a promising strategy for prevention of ischemic stroke." (PMID 33935731, 2021). "An increasing body of evidence indicates that activation of PI3K/Akt and inhibition of GSK3β play a neuroprotective role in many brain injury models, including experimental ischemic stroke, subarachnoid hemorrhage-induced early brain injury, traumatic brain injury, and intracerebral hemorrhage." (PMID 32082121, 2019). "Therefore, this study aimed to investigate whether NBP enhances angiogenesis and vasodilation following ischemic stroke and to elucidate the potential involvement of the Akt/GSK‐3β pathway." (PMID 41373119, 2025). "Thus, eIF4E2's ISGylation could potentially modulate GSK3β kinase activity and may regulate the eIF4E2-GSK3β pathway, playing a critical role in ischemic stroke." (PMID 41022323, 2025). "Therefore, it is possible to inhibit ERK and GSK3β, concurrently, to treat ischemic stroke." (PMID 36015166, 2022). "Therefore, we raised the hypothesis that RIP1K and GSK3β may play a key role in ischemic stroke-induced astrogliosis and glial scar formation, and there might be an interaction between them." (PMID 32595496, 2020).
ischemic stroke (continued). "These were in comply with those studies that showed the influence of lithium, as GSK-3β inhibitor, on neuroblastoma SH-SY5Y human cells as well as its effect in vivo and invitro in models of ischemic stroke induced excitotoxicity." (PMID 40381124, 2025). "Prior studies suggest that Gsk3b inhibition can protect the BBB and alleviate ischemia-reperfusion injury in ischemic stroke models." (PMID 40529227, 2025). "Activation of the PI3K/AKT pathway has also been found to significantly reduce neuronal damage in ischemic stroke, as AKT phosphorylates its downstream target GSK-3β, and the PI3K/AKT/GSK3β pathway is essential for maintaining cell survival." (PMID 37645701, 2023). "In conclusion, BBF prevented IAA-induced toxicity in HT22 cells and MCAO-induced neurological and behavioral abnormity in rats, possibly via the inhibition of the ERK and GSK3β pathways, indicating the potential use of BBF for treating ischemic stroke." (PMID 36015166, 2022). "Collectively, the present results showed that TSTT-induced axonal remodeling, at least in part, via activating PI3K/AKT followed by inactivated GSK-3β and attenuated phosphorylation of CRMP-2 after ischemic stroke." (PMID 34955834, 2021). "Our results suggest that GSK3β and RIP1K might be potential therapeutic targets for ischemic stroke." (PMID 32595496, 2020). "Therefore, we next explored the interaction between GSK3β and RIP1K during ischemic stroke-induced glial scar formation." (PMID 32595496, 2020). "One interesting finding from the present study is that GSK3β and RIP1K may interact to regulate ischemic stroke-induced glial scar formation." (PMID 32595496, 2020). "Two proteins, inducible nitric oxide synthase (NOS2) and glycogen synthase kinase-3 beta (GSK3B), were highlighted by the network pharmacology analysis, which may be the potential therapeutic targets for the GSTTF against ischemic stroke." (PMID 31640179, 2019).